SNORD114-13 (small nucleolar RNA, C/D box 114-13)
Synonyms: 14q(II-13)
Gene: Small nucleolar RNA gene on chromosome 14 (100,969,879 to 100,969,952, forward strand). Ensembl gene ENSG00000201247.
Gene Ontology:
Biological process: RNA processing
Cellular component: nucleolus
Homologues: Orthologues: chimpanzee SNORD114-13 (97% identical), macaque SNORD114-13 (93% identical), mouse Gm23736 (78% identical), rat Snord113l1 (74% identical), mouse Gm22981 (73% identical), rat LOC120093391 (70% identical), mouse AF357341 (65% identical), mouse Gm25856 (64% identical), mouse AF357428 (58% identical). Paralogues in human: SNORD114-3 (85% identical), SNORD114-11 (84% identical), SNORD114-21 (82% identical), SNORD114-23 (82% identical), SNORD114-5 (82% identical), SNORD114-15 (81% identical), SNORD114-28 (81% identical), SNORD114-16 (80% identical), SNORD114-17 (80% identical), SNORD114-26 (80% identical), SNORD114-9 (80% identical), SNORD114-14 (78% identical), and 26 more.